MIR3143 (microRNA 3143)
Synonyms: hsa-mir-3143; mir-3143
Gene: MicroRNA gene on chromosome 6 (27,147,626 to 27,147,688, forward strand). Ensembl gene ENSG00000265565.
Diseases named in the same sentence as MIR3143 in open-access papers:
MIR3143 is named in the same sentence as 2 diseases in open-access papers, as found by Europe PMC text mining. Sharing a sentence is not in itself a finding about the gene and the disease. The quoted sentences say what the papers report.
depression (1 paper, 2020). "Three replicated loci were previously reported (ITIH3, FHIT, BAG5), but the other seven (ZNF804A, MIR3143, PSORS1C2, STK19, SPATA31D1, RTN1, TCF4) were novel for depression." (PMID 30626913, 2020).
MIR3143 also shares sentences with these, for which no sentence is quoted: schizophrenia (1 paper).